CCL5 (C-C motif chemokine ligand 5)
Diseases named in the same sentence as CCL5 in open-access papers (continued):
Sharing a sentence is not in itself a finding about the gene and the disease.
tumor (continued). "used a mixture of 50:50 PG/VG and nicotine (24 mg/mL) and identified the protumoral role of tumor-infiltrating suppressive macrophages upon their CCR5:CCL5 crosstalk with tumor cells, enhanced by exposure to a mixture of PG/VG and nicotine." (PMID 39221247, 2024). "It is believed that monocyte-attracting chemokines are primarily responsible for macrophage infiltration in tumors, such as CCL2 and CCL5 that can be produced by tumor cells, endothelial cells, macrophages, and fibroblasts within the tumor microenvironment." (PMID 39628476, 2024). "In GBM infected with OV-Cmab-CCL5, there was an increase in NK cell activity, T cell activity, and macrophage activity along with a decrease in tumor size." (PMID 39055561, 2024). "In in vivo settings, CCR5-engineered NK cells have reduced tumor size and prolonged mice survival in combination with CCL5-expressing OVs." (PMID 39066359, 2024). "The expression of ZBTB32 and CCL5 was also determined by western blot analysis using tumor masses, and the mutation of di‐methylated Lys148 inhibited ZBTB32 and CCL5 expression, which was consistent with the results in A549 and H460 cells." (PMID 38873823, 2024). "CCL5 can mediate antitumor immunity by specifically recruiting antitumor CD8+ T cells to tumor sites, serving as a reminder of the highly contextual effects of chemokines in cancer." (PMID 38786066, 2024). "It has been shown that Foxp3 works synergistically to control the recruitment of chemokine CCL5 to Treg cells in the tumor microenvironment to promote the immune escape of PDAC." (PMID 38919615, 2024). "A study using an orthotopic 4T1 breast tumor model showed that the autocrine CCL5/CCR5 axis sustained an influx of immunosuppressive myeloid cells into the tumor and discouraged cytotoxic CD8+ T cells." (PMID 38786066, 2024). "Chemokines such as CCL2 and CCL5 attract immune cells to the tumor site, facilitating a robust immune attack, critical for combating tumor heterogeneity and adaptive resistance mechanisms." (PMID 39103972, 2024). "Our in vitro data showed that the OSU13-mediated induction of interferon responses, chemokine CCL5, and several other proimmunogenic factors in tumor cells was STING dependent." (PMID 38900577, 2024). "CCL4 and CCL5 are involved in attracting endogenous T cells and monocytes to the tumor site, while GM-CSF mediates the differentiation and activation of APC, as well as activation of T cells." (PMID 38856749, 2024). "Our study reveals that intratumor injection of E. coli MG1655 normalizes tumor vasculatures and reprograms tumor-associated macrophages into M1 phenotype that produce abundant CCL5, together facilitating tumor infiltration of adoptively transferred T cells." (PMID 39572541, 2024). "Subsequent subcutaneous tumorigenesis experiments revealed that CCL5 can enhance the tumorigenicity of tumor cells." (PMID 39227943, 2024). "CCL5 interaction with CCR5 promotes tumor development, invasion, angiogenesis, and immune cell recruitment to the TME." (PMID 39126091, 2024). "In comparison to control tumors, those overexpressing miR-29 exhibited the following changes: (i) Elevated levels of anti-tumor cytokines such as CCL5 and CCL11, the transmembrane protein CD40, and the angiogenesis inhibitor endostatin." (PMID 38890285, 2024). "In ccRCC samples with upregulated CCL5, there is a significant increase in the proportion of CCL5 + tumor-associated macrophages (TAMs) and PD-L1 + CD68 + TAMs, indicative of a typical immunosuppressive tumor immune microenvironment." (PMID 39014460, 2024). "In PDAC, tumor cells express CCL5 and CCR5, and CCL5–CCR5 signaling promotes cancer cell proliferation, invasion, and metastasis." (PMID 39261943, 2024). "We further define a glutamate-dependent neuron-oligodendrocyte interaction that results in IL-1β-mediated TAM production of Ccl5 production and tumor formation." (PMID 38308315, 2024).
tumor (continued). "Previously, it was shown that TGF-β depletion enhanced the expression of CCL5 in different tumor models." (PMID 39298276, 2024). "Our data demonstrate that anti-PD1 therapy expands these Ccl5-expressing dysfunctional CD8 T cells (CD8Ex1) within the lungs of tumor-burdened mice, potentially limiting the effectiveness of anti-PD1 therapies." (PMID 38536921, 2024). "These tumours express less CCL5 chemokine and other major cytokines and chemokines involved in lymphocyte chemotaxis such as CXCL10." (PMID 39261716, 2024). "Pro-tumor factors that cause immunosuppression in the tumor microenvironment, such as CCL2, CCL5, neutrophil elastase (NE), and cathepsin G (CG), are expressed more often in N2 neutrophils, along with a greater expression of arginase." (PMID 39090094, 2024). "Tumor-associated neutrophils are polarized by TME-triggered ER stress and promote PDAC progression by upregulating CCL5 and Nectin2 expression." (PMID 39261943, 2024). "Our study revealed that MIR155HG abrogates its intrinsic oncogenic role by inducing tumor CCL5 secretion dependent on YBX1, thus promoting the recruitment of CD8+ T cells." (PMID 39043648, 2024). "TAM depletion results in reduced tumor proliferation (%Ki67+ cells), Blbp+ and Olig2+ cell content (%Olig2+ and %Blbp+ cells) and Ccl5 expression." (PMID 38308315, 2024). "The cGAS-STING pathway can potentially inhibit immune escape by IFNβ1/CCL5-mediated infiltration of CTLs and can also promote tumor growth by activating VEGF signaling and immune checkpoints such as the PD-1 axis." (PMID 39201585, 2024). "In MC38 tumor tissues, the relative mRNA expression of CCL5 was significantly decreased in aged mice, while XCL1 showed a moderate decrease." (PMID 38725070, 2024). "It is recruited to the tumor focus by chemokines such as CCL2 and CCL5 to exert the tumor immunosuppressive function and jointly form the immunosuppressive tumor myeloid microenvironment." (PMID 38279145, 2024). "Concurrently, KTC1101 treatment influences the expression of tumor-derived immunomodulatory factors like CCL5 and CXCL10 that determine T-cell infiltration." (PMID 38486218, 2024). "Soluble pro‐inflammatory factors such as CCL2, CCL5, and CCL18 secreted by TAMs from the primary tumor have been implicated in the formation of a pre‐metastatic niche in distant organs such as the lungs and the bones, increasing tumor cell colonization." (PMID 38426622, 2024). "In vitro studies have shown that the upregulation of CCL5 leads to increased recruitment of macrophages and enhances the migration and invasive capabilities of tumor cells." (PMID 38716256, 2024). "As RANTES/CCL5 has been previously linked to MMP9 expression and tumor cell migration, we confirmed induction of CCL5 expression using ELISA." (PMID 39286811, 2024). "We found that compared to the primary and metastatic sites of the tumor, CCL5 was in a high expression state in CTCs." (PMID 39227943, 2024). "CCL5 has also been connected to tumor proliferation, invasion, migration, and reconstruction of the extracellular matrix in BCa; however, prognostic studies have found CCL5 to be anti-tumorigenic as well." (PMID 39409924, 2024). "Furtherly, we revealed that the interaction between MIR155HG and YBX1 resulted in upregulation of CCL5 expression to recruit more CD8+ T cells in tumor environment." (PMID 39043648, 2024). "FAK reduces the number and activity of anti-tumor cells by promoting the production of type ǀ collagen and mediating CCL5 to increase the infiltration of Tregs." (PMID 38590651, 2024). "The CCL5/CCR5 chemokine axis, shown to be associated with various cancer types, activates tumor progression through different pathways, such as increasing tumor growth and promoting extracellular matrix remodeling, migration, invasion, and angiogenesis." (PMID 39329983, 2024). "CCL5 participates in anti-tumor activity and physiological processes such as cell migration and immune response." (PMID 39334887, 2024).
tumor (continued). "In contrast to tumor gene expression, the levels of systemic CCL5, CXCL9 and CXCL10 in baseline serum samples were similar among all patients, regardless of their response to anti-HER2 antibody-based neoadjuvant treatment." (PMID 38167224, 2024). "When compared with normal group, CD56bri_CCL5 cells in tumor demonstrated an increased interaction weight with macrophage cells through the MIF-(CD74+ CD44) ligand-receptor pair." (PMID 38552055, 2024). "We discovered that the lymphocyte infiltration and the expression of CD8A and CCL5 increased in tumor tissue after combination therapy." (PMID 39183447, 2024). "In the MIBC subgroup analysis this prognostic effect was also found for OS, DSS, and RFS in CCL5 IC-negative patients in the tumor stage 3 + 4 subgroup or in the luminal molecular subtype subgroup." (PMID 38928033, 2024). "The recruitment of tumor-associated macrophages (TAMs) to tumor sites is mediated by chemokines such as CCL2, CCL5, CCL7, CXCL1, CXCL2, and CXCL4, which promote tumor survival." (PMID 39769501, 2024). "As proof of principle demonstration, we investigated the expression of SR‐B1 and CCL5 in GBM samples and found that the protein levels of SR‐B1 and CCL5 were obviously elevated in tumor tissues versus in the peritumor tissues." (PMID 38049204, 2024). "Chemokines such as CCL5 recruit antitumor immune cells to enhance antitumor immunity while recruiting immunosuppressive lymphocytes such as Treg cells, leading to tumor immune escape." (PMID 39007138, 2024). "CCL5 was significantly increased in all irradiated tumor tissues, with the highest concentration observed in PI16/2 samples both in the 16 Gy and 2 Gy volumes." (PMID 39397001, 2024). "CCL5 expression by CD4+ tumor-associated lymphocytes in the TME and GC cells causes increased CCL5 release and enhances GC cell line growth." (PMID 39329983, 2024). "Deoxycytidine blockade of TAMs impairs the cytotoxic activity of gemcitabine in PDAC tumor cells, and activation of the CCL5/CCR5/Sp1/CD44 signaling pathway in TAMs also inhibits the antitumor efficacy of gemcitabine." (PMID 38982491, 2024). "Arginase-1, produced by myeloid cells, impairs antitumor response, and CCL5, mainly expressed by T lymphocytes, macrophages, platelets, tumor cells and MDSCs, resulted in a direct CCR5-dependent recruitment of Treg cells in TME." (PMID 37142825, 2024). "The C-C chemokine receptor 5 (CCR5)–CCL5 chemotaxis pathway has been identified as a mechanism for NK cell infiltration into a tumor." (PMID 39066359, 2024). "Tumor cells can recruit macrophages into TME by triggering the CCL5/CCR5 signaling pathway and raising the quantity of M2-like macrophages." (PMID 38341519, 2024). "Chemokines CCL5 and CCL4 have been associated with the modulation of TIME, particularly with respect to immune cell infiltration and tumor progression." (PMID 39001353, 2024). "RT-qPCR was employed to detect the mRNA levels of these chemokines in tumor tissues of our exercise models, confirming that Ccl5, Cxcl10, Cxcl9, and Cxcl11 were significantly increased in Ex mice compared to the Ctrl group." (PMID 38622609, 2024). "The tumors that co-expressed RKIP and CCL5, however, were unable to show this reduction in pro-tumor markers." (PMID 36765912, 2023). "In CRC, CCL5 blockade reduced tumor xenograft growth, decreased the migration of tumor cells, reduced liver metastases, and decreased the infiltration of Tregs in the tumor." (PMID 36831453, 2023). "Nuclear FAK has been shown to promote tumor progression by regulating the transcription of cytokines/chemokines, including CCL5, TGFβ2, IL33, and VEGFβ, which in turn drive the establishment of an immunosuppressive microenvironment." (PMID 37845206, 2023). "The activation of the Wnt/β-catenin pathway by CTNNB1 mutations contributes to a decline in TIL by inducing downregulation of the chemokines CCL4 and CCL5 that attract dendritic cells and T cells into tumor tissue." (PMID 37190307, 2023).
tumor (continued). "Irradiation caused the release of γH2AX (a marker of DNA damage), followed by elevated levels of chemokines CXCL1, CXCL2 and CCL5 to recruit TANs to the tumor site." (PMID 37833255, 2023). "Reduction of chemokine (C-C motif) ligand 5 (CCL5) resulted in reduced tumor-infiltrating lymphocyte (TIL) cells." (PMID 37660142, 2023). "For example, CCL5 signaling through CCR5 supports recruitment of anti-tumor natural killer cells and cytotoxic T cells, but also stimulates pro-tumor, tissue-resident myeloid cells and lymphocytes." (PMID 37006247, 2023). "Upon secretion of CCL-5 from the LECs, tumor cells expressing the receptor for CCL-5 (CCR-5) will be recruited to the LECs and presumably integrated into the lymphatic system for further metastatic colonization." (PMID 36768435, 2023). "Overexpression of EZH2 in LC cells promotes the production of tumor-derived CCL5, leading to recruitment of M2-like macrophages and immunosuppressive Treg cells, which can facilitate tumor proliferation and metastasis while inhibiting CD8+ T cells." (PMID 37909018, 2023). "Intravenous injection of 4T1 tumor cells rendered NK cells recruited to the lungs through IL-33 stimulation, which depended on C-C motif chemokine ligand 5 (CCL5) expressed by eosinophils and CD8+ T cells." (PMID 37508545, 2023). "On the other hand, as a double-edged sword, the CCL5/CCR5 axis also promotes antitumor immunity by recruiting tumor-infiltrated-T cells and dendritic cells." (PMID 36675305, 2023). "CCL5 is an important chemokine that is primarily secreted by tumor stromal cells under the stimulation of BC cells, and it is closely associated with the invasiveness and metastasis of BC." (PMID 36765683, 2023). "CCL5 is expressed by T lymphocytes, macrophages, platelets, synovial fibroblasts, tubular epithelium, and certain types of tumor cells." (PMID 36983384, 2023). "IFN-β, IL-6, CXCL10, CCL2, and CCL5 have been reported to be induced in tumor cells by ATRi plus RT in vivo and/or in vitro." (PMID 36810257, 2023). "On the other hand, another hub-chemokine, CCL5, is also found to be capable of inducing the immunosuppression in the tumor microenvironment and subsequent cancer progression and poor prognosis in KIRC via CCL5-dependent mast cell infiltration." (PMID 37484803, 2023). "The recruitment and expansion of DC in the TME are dependent on several cytokines and chemokines, such as NK cell-derived FLT3L, XCL1, CCL5, as well as tumor-derived CCL4." (PMID 38008741, 2023). "Direct contact between MDA-MB-231 tumor cells and ASCs or adipocytes in this model promoted the expression of C-C motif chemokine ligand 5 (CCL5) and specifically the corresponding receptor C-C chemokine receptor type 1 (CCR1)." (PMID 37444610, 2023). "Specifically, an oncolytic adenovirus has been exploited to convey chemokine ligand 5 (CCL5) chemokine to the tumor cells." (PMID 36564524, 2023). "Preclinical modeling has demonstrated its importance in recruiting CD8+ T cells to the tumor microenvironment via CCL5, CXCL9, and CDCL10 chemokine release." (PMID 37903733, 2023). "Overall, although future investigations using animal models will be useful to strengthen our results, the present study highlights a novel tumor suppressive role played by DHEA through CCL5 reduction in malignant breast cancer." (PMID 36765778, 2023). "Recruited macrophages by CCL5 have been shown to secrete collagen and collagen deposition factors and promoted tumor recurrence." (PMID 36794651, 2023). "CCL5 gene expression in macrophages also increased with tumor progression, which confirmed that macrophages secreted more CCL5 in the middle and advanced disease stages." (PMID 37553567, 2023). "The role of CCL5 in inducing GR was further investigated using clinical data and tumor sections obtained from 48 PAAD patients over three years, inhibitors, and short hairpin RNA (shRNA)." (PMID 37553567, 2023).
tumor (continued). "Consistent with the in vitro cell experiments, we observed that PTP 9 and anti-PD-1 cotreatment induced a significant increase in tumor expression of Cxcl11, Ccl5, Stat1, Stat3, Tap1, Irf1, Casp8, and Pdl1, compared with anti-PD-1 treatment alone." (PMID 36968224, 2023). "CCL2 and CCL5 have been suggested to act as important mediators between tumor and host cells in the tumor microenvironment." (PMID 36766725, 2023). "CCL5 itself attracts conventional type 1 dendritic cells to the tumor and promotes T cell infiltration into the tumor." (PMID 38133557, 2023). "Secretion of VEGFC can induce lymphangiogenesis, while increased CCL5 in tumor microenvironment can form a concentration gradient to recruit M2 TAM, then promote TNF‐α secretion to increase lymphatic permeability." (PMID 37409440, 2023). "Neutralization with CCL5 antibody or the deletion of Ccl5 dramatically attenuated tumor growth in vivo." (PMID 37891793, 2023). "CCL5 has previously been tested in murine models as adjuvant therapy for tumor lysate-pulsed DC vaccines." (PMID 37505292, 2023). "The expression of the pro-inflammatory chemokines CCL5 and CCL2 increased in HIF–1-deficient tumors, which in turn increased the infiltration of cytotoxic lymphocytes into the tumor." (PMID 37056346, 2023). "Fc IgG1 induces Fc receptor-mediated NK cytotoxicity and macrophage phagocytosis and anti-EGFR tethers CCL5-Fc to tumor cells." (PMID 37325516, 2023). "Increasing evidence suggests that MDSCs also play an important role in the development of HCC, CCL2 and CCL5 from tumour cells and facilitate infiltration of MDSCs into the TME." (PMID 37542324, 2023). "Tang and colleagues showed that ovarian CSCs differentiate into endothelial cells (ECs) and promote tumour angiogenesis through autocrine C-C Motif Chemokine Ligand 5 (CCL5) signalling." (PMID 38041196, 2023). "Similar results were achieved in another study where IL-33 activated NK cells in the blood and recruited them to the TME through CCL5 to suppress metastatic tumor development." (PMID 37587450, 2023). "Overexpression of EIF4E3 can induce the expression of CCL4/CCL5, playing a significant role in monocyte differentiation in the tumor microenvironment." (PMID 37664112, 2023). "The CCL5/CCR5 axis plays an important role in establishing an immunosuppressive tumor microenvironment." (PMID 37845206, 2023). "Among the identified MEP-secreted factors we note the presence of CXCL16 and CCL5, which are known to activate anti-tumor immune cells such as CD8 + T cells and NK cells in different tumor models." (PMID 36646904, 2023). "Previous studies have shown that CCL5 directly acts on tumor cells to change tumor metastatic rates." (PMID 37141250, 2023). "Chemokine ligand 5 (CCL5) has also been identified as one of the key chemokines recruited by macrophages in tumor cells." (PMID 37909018, 2023). "These G protein-coupled receptors have been reported to be involved in CCL5-mediated tumor progression and invasion to varying extents depending on the particular context and cancer type." (PMID 37444610, 2023). "CCL5 is thought to aid tumor cells’ escape the immune system, which is essential in tumor survival and progression in breast and other cancers." (PMID 37759462, 2023). "Chemokine axes such as C-C motif chemokine ligand 2 (CCL-2)/C-C motif chemokine receptor 2 (CCR2) and CCL-5/CCR5 can recruit monocytes/macrophages from the blood to the tumor region." (PMID 36902024, 2023). "Based on the KM plotter database, the survival rates of patients with high expression of CD73 or CCL5 were significantly decreased in the CD8+ T-cell-rich groups, indicating that CD73 and CCL5 promote tumor progression by inhibiting CD8+ T-cell priming." (PMID 37291128, 2023). "The chemokine CCL5 has been also proposed to participate in the incorporation of MCs to tumors, since it was observed expressed in smooth muscle tumor cells and tumor-infiltrating MCs express the CCR3 receptor." (PMID 37047288, 2023).